PARGP1 (PARG pseudogene 1)
Gene: Transcribed unprocessed pseudogene on chromosome 10 (45,888,165 to 45,972,154, reverse strand). Ensembl gene ENSG00000239883.
Diseases named in the same sentence as PARGP1 in open-access papers:
PARGP1 is named in the same sentence as 3 diseases in open-access papers, as found by Europe PMC text mining. Sharing a sentence is not in itself a finding about the gene and the disease.
PARGP1 shares sentences with these, for which no sentence is quoted: cancer (1 paper); lung carcinoma (1); tumor (1).